PSCA (prostate stem cell antigen)
Diseases named in the same sentence as PSCA in open-access papers (continued):
Sharing a sentence is not in itself a finding about the gene and the disease.
prostate carcinoma (continued). "The modified scFvs recognize either prostate stem cell antigen (PSCA), a prostate cancer (PCa) specific antigen or CD33, a cell surface glycoprotein specific for hematopoietic cells of myeloid origin." (PMID 24699869, 2014). "Prostate stem cell antigen (PSCA) belongs to the Thy-1/Ly-6 family of the glycosylphosphatidylinositol-anchored cell membrane glycoprotein, which can overexpress in prostate cancer tissues." (PMID 24330823, 2013). "The aim of this study was to establish a tumor model in mice with the expression of luciferase (Luc) and human prostate stem cell antigen (PSCA), in order to evaluate the activities of anticancer drugs or vaccines for prostate cancer." (PMID 24223645, 2013). "PSCA, a glycosylphosphatidylinositol- (GPI-) anchored cell-surface glycoprotein, has been reported to be overexpressed in more than 80% of prostate cancers." (PMID 23984394, 2013). "The prostate stem cell antigen (PSCA) is a notable antigen; owing to its overexpression in prostate cancer, and exclusively in metastatic tissues; thus, it is a promising candidate for prostate cancer immunotherapy." (PMID 36969009, 2023). "Nevertheless, prostate cancer has been one of the most widely investigated solid tumor types for CAR-T therapies, as clinical-stage cell products have most often targeted prostate-specific membrane antigen (PSMA) and prostate stem cell antigen (PSCA)." (PMID 37966111, 2023). "Target antigens for CAR T cells in prostate cancer include prostate-specific membrane antigen (PSMA), prostate stem cell antigen (PSCA), KLK2, and six-membrane epithelial antigen of the prostate-1 (STEAP-1), mainly as monotherapies and with limited success thus far5–9." (PMID 37660083, 2023). "In addition to PSMA, prostate stem cell antigen (PSCA), another TAA for prostate cancer, is a membrane glycoprotein predominantly expressed in prostate cancer, which is expressed in 94% (105/112) of primary prostate tumors and 100% (9/9) of bone metastases." (PMID 36497465, 2022). "GOLM1, CD24, PSCA, and the gene fusion TMPRSS2-ERG were selected as overexpressed mRNAs in prostate cancer, whereas ANXA3 and SLC45A3 were selected as underexpressed mRNAs in prostate cancer for evaluation." (PMID 33172003, 2020). "Prostate stem cell antigen (PSCA) is a glycosylphosphatidylinositol-anchored cell-surface protein belonging to the Ly-6/Thy-1 family of cell-surface antigens, initially identified in a human prostate cancer cell xenograft." (PMID 32290196, 2020). "Various cell surface markers have been evaluated for diagnosis and treatment of patients suffering from prostate cancer, including prostate specific antigen (PSA), prostatic acid phosphatase (PAP), prostate stem cell antigen (PSCA), and prostate specific membrane antigen (PSMA)." (PMID 31466360, 2019). "PSCA is a 123-amino-acid glycoprotein related to the Ly-6 family of cell-surface protein, and first identified in the LAPC-4 prostate xenograft model of human prostate cancer in 19986." (PMID 27001215, 2016). "Currently, molecular targeted therapies for prostate cancer undergoing clinical trials include therapies against prostate-specific membrane antigen (PSMA) and prostate stem cell antigen (PSCA), anti-angiogenesis drugs, and anti-tumor cell signaling COX-2 inhibitor drugs." (PMID 25881543, 2015). "PSCA belongs to the LY-6/Thy-1 family and is highly expressed in normal prostate and further up-regulated in prostate cancer, which is also found in non-prostatic malignancies including gastric cancer." (PMID 26124924, 2015). "The most promising prostate cancer markers among others are the prostate-specific membrane antigen (PSMA), prostate stem cell antigen (PSCA), early prostate cancer antigen (EPCA), enhancer of zeste homolog gene 2 (EZH2), and the urokinase plasminogen activator (uPA)." (PMID 24877145, 2014).
prostate carcinoma (continued). "In addition, prostate cancer expresses numerous TAAs which include the Prostate Specific Antigen (PSA), Prostatic Acid Phosphatase (PAP), Prostate Specific Membrane Antigen (PSMA), Prostate Stem Cell Antigen (PSCA) and Six Transmembrane Epithelial Antigen of the Prostate (STEAP)." (PMID 26161151, 2015).
gastric cancer (39 papers, 2008 to 2025). A primary or metastatic malignant neoplasm involving the stomach. "In this meta-analysis, we systematically evaluated the association between PSCA rs2976392 polymorphism and the risk of gastric cancer." (PMID 40741413, 2025). "In conclusion, our meta-analysis provides comprehensive evidence that the PSCA rs2976392 polymorphism is significantly associated with an increased risk of gastric cancer, especially in Asian populations." (PMID 40741413, 2025). "They reported that the lead eQTL for PSCA is rs2920283, and an upregulated PSCA mRNA expression in gastric tissue was observed in gastric cancer risk allele carriers." (PMID 36010338, 2022). "Studies have confirmed that prostate stem cell antigen (PSCA) rs2294008 C>T polymorphism is related to gastric cancer susceptibility, but some studies have reached the opposite conclusion." (PMID 41822099, 2022). "PSCA-rs2294008 is a GWAS-identified susceptibility polymorphism for gastric cancer both in Japan and worldwide." (PMID 34771687, 2021). "The aim of this study was avaluating the association of rs4072037G > A polymorphism in MUC1 and rs2294008 C > T in PSCA gene with risk of gastric cancer in northern Iran." (PMID 32660489, 2020). "The association of PSCA (5057C > T) variant was described in Korea and Japan population for the first time and the T allele was reported as a risk factor for gastric cancer." (PMID 32660489, 2020). "Recently, a meta-analysis demonstrated that of the PSCA rs2976392 G>A polymorphism is associated with increased cancer risk, especially for gastric cancer and bladder cancer." (PMID 31983162, 2020). "Whereas, for PSCA rs2976392, we also established that PSCA rs2976392 polymorphism is significantly associated with an increased risk of gastric cancer in the Chinese population." (PMID 31416884, 2019). "In this hospital-based case–control study, we investigated the association of the two PSCA gene rs2294008 C > T and rs2976392 G > A polymorphisms with the risk of gastric cancer in 549 patients and 592 healthy controls of Chinese origin." (PMID 31416884, 2019). "The PSCA rs2976392 polymorphism was also reported to relate to the increased risk of gastric cancer in some previous studies, but in some other studies including meta-analyses no such association was suggested." (PMID 31416884, 2019). "In a two-stage genome-wide association study (GWAS) conducted in the Korean and Japanese populations, the prostate stem cell antigen (PSCA) gene polymorphisms were reported to be associated with an increased risk of gastric cancer." (PMID 31416884, 2019). "In summary, our findings verified that the two PSCA gene rs2294008 C > T and rs2976392 G > A polymorphisms were significantly associated with an increased risk of gastric cancer in the Chinese population." (PMID 31416884, 2019). "A similar association with gastric cancer risk was also found for the PSCA gene rs2976392 G > A (GA vs. GG, OR = 1.61, 95% CI = 1.25–2.07, P<0.001 and GA+AA vs. GG, OR = 1.52, 95% CI = 1.20–1.92, P<0.001)." (PMID 31416884, 2019). "In conclusion, our findings verified that the PSCA gene rs2294008 and rs2976392 polymorphisms were both significantly associated with an increased risk of gastric cancer in the Chinese population." (PMID 31416884, 2019). "Previously, GWASs had indicated that the two PSCA gene rs2294008 C > T and rs2976392 G > A polymorphisms were significantly associated with the risk of gastric cancer in the Chinese, Japanese, Korean and Caucasian populations." (PMID 31416884, 2019). "The PSCA gene rs2294008 C > T was found to significantly increase the risk of gastric cancer (CT vs. CC, OR = 1.55, 95% CI = 1.20–1.99, P<0.001 and CT+TT vs. CC, OR = 1.38, 95% CI = 1.09–1.74, P=0.008)." (PMID 31416884, 2019). "Rs2294008 C > T and rs2976392 G > A polymorphism, the most widely studied polymorphisms in the PSCA gene, have demonstrated to be associated with an increased risk of gastric cancer." (PMID 31416884, 2019).
gastric cancer (continued). "In view of this, we carried out a case–control study to investigate the association between PSCA gene rs2294008 C > T and rs2976392 G > A polymorphism and the risk of gastric cancer in the Chinese population." (PMID 31416884, 2019). "Although the gastric cancer-risk T allele is associated with a higher expression of PSCA mRNA, PSCA expression in gastric cancer tissues decreases." (PMID 29423095, 2018). "Previous genome-wide association studies have revealed the association of SNP rs2294008 in Prostate Stem Cell Antigen (PSCA) with two H. pylori related diseases, gastric cancer and duodenal ulcer." (PMID 29423095, 2018). "Meanwhile, PSCA rs2976392 G>A polymorphism significantly increased cancer risk only in gastric cancer." (PMID 28881685, 2017). "The results suggested that significantly elevated cancer risk was associated with the PSCA rs2294008 C>T polymorphism levels, particularly in patients with gastric cancer and bladder cancer." (PMID 28881685, 2017). "This current meta-analysis provided statistical evidence supporting that the PSCA rs2294008 C>T and rs2976392 G>A polymorphisms increased the risk of cancer, especially in gastric cancer and bladder cancer." (PMID 28881685, 2017). "This study aimed to investigate the association between two polymorphic variants of PSCA gene (rs2294008 and rs9297976) and the susceptibility to gastric cancer in Uzbekistan." (PMID 29138729, 2016). "In a two-stage GWAS on gastric cancer conducted in Japanese and Korean population, two SNPs (rs2294008 C>T and rs2976392 G>A) in the prostate stem cell antigen (PSCA) gene were found to be significantly associated with increased stomach cancer risk." (PMID 26124924, 2015). "Based on the statistical evidence, we can draw a conclusion that the rs2294008 polymorphism of PSCA gene is likely to play a role in cancer carcinogenesis, especially in gastric cancer and bladder cancer." (PMID 26308216, 2015). "FPRP analysis indicated that the significant association between PSCA rs2294008 C>T and stomach cancer risk was noteworthy under homozygous model." (PMID 25658482, 2015). "This meta-analysis demonstrated that both of the PSCA rs2294008 C>T and rs2976392 G>A polymorphisms are associated with increased cancer risk, especially for gastric cancer and bladder cancer." (PMID 26124924, 2015). "A similar association with stomach cancer risk was also found for the PSCA rs2976392 G>A polymorphism (AG vs. GG: adjusted OR = 1.30, 95% CI = 1.02–1.65, and AG/AA vs. GG: adjusted OR = 1.26; 95% CI = 1.00–1.59)." (PMID 25658482, 2015). "For example, in stomach cancer, polymorphisms in the PSCA gene have been shown to be associated with the development of diffuse-type gastric adenocarcinoma, a histologic variant traditionally associated with poor clinical outcome." (PMID 18778478, 2008). "For instance, the PSCA gene, which plays a crucial role in cell proliferation and differentiation, has been linked with the progression of gastric cancer, suggesting that alterations in this gene could contribute to cancer pathogenesis." (PMID 39355481, 2024). "PSCA polymorphisms are also involved in the development of gastric cancer." (PMID 38627732, 2024). "Additionally, genetic variants of glutathione S-transferase theta 1 (GSTT1) and prostate stem cell antigen (PSCS) related to DU were inversely associated with gastric cancer risk in Japanese and Indians, respectively." (PMID 36678166, 2023). "Consequently, it was confirmed that PSCA rs2294008 polymorphism leads to an increased risk of gastric cancer." (PMID 41822099, 2022). "Although most studies on the relationship between PSCA genetic predisposition and gastroduodenal diseases and gastric cancers have focused on rs2294008 in PSCA, there is information on the association between the risk of gastric cancer and other PSCA genetic variations in the literature." (PMID 36010338, 2022).
gastric cancer (continued). "The T allele of rs2294008, which is considered a risk allele in gastric cancer, upregulated the expression of PSCA mRNA compared with the C allele of rs22904008 both in normal gastric and gastric cancer tissues, and the prognosis worsened with increased mRNA expression." (PMID 36010338, 2022). "Several genetic risk loci of gastric cancer are known, ranging from the historically identified blood type A to the markers discovered through genome-wide association study, including prostate stem cell antigen (PSCA), mucin 1 (MUC1) and other genes." (PMID 34359626, 2021). "In addition, Genome-Wide Association Studies (GWAS) proposed genetic diversities like rs4072037G > A (5640G > A) in MUC1 gene and rs2294008C > T (5057C > T) polymorphisms in PSCA (Prostate Stem Cell Antigen) gene as genetic risk factors in gastric cancer." (PMID 32660489, 2020). "We found that the PSCA gene rs2294008 CT/TT and rs2976392 GA/AA genotypes significantly increased the risk of gastric cancer in the Chinese population, especially in the younger subjects, the males, the never-smokers, the ever-drinkers and the subjects with non-cardia tumor site." (PMID 31416884, 2019). "To further confirm the association, we conducted a replication study and found that the PSCA rs2294008 contributed to the increased gastric cancer susceptibility (CT vs. CC, OR = 1.55, 95% CI = 1.20–1.99, P<0.001 and CT+TT vs. CC, OR = 1.38, 95% CI = 1.09–1.74, P=0.008)." (PMID 31416884, 2019). "Therefore, it is necessary to investigate the role of PSCA polymorphisms in the etiology of gastric cancer." (PMID 31416884, 2019). "rs2294008 was associated with PSCA mRNA expression in normal gastric tissues and gastric cancer." (PMID 29423095, 2018). "Interestingly, individuals with a nonsense SNP (rs138377917[A]) of PSCA that lack functional PSCA protein is associated with a low risk for gastric cancer." (PMID 29423095, 2018). "Moreover, as the most extensively studied SNPs in the PSCA gene, rs2294008 C>T and rs2976392 G>A are shown to be associated with increased risk of bladder and stomach cancers." (PMID 28881685, 2017). "Our findings support that PSCA rs2294008 and rs9297976 polymorphism may contribute to the susceptibility to gastric cancer." (PMID 29138729, 2016). "In summary, the results of our research provided preliminary evidence that PSCA rs2294008 and rs9297976 polymorphism may contribute to gastric cancer risk in Uzbekistan." (PMID 29138729, 2016). "Recently, three genome-wide association studies have identified the PSCA (prostate stem cell antigen) rs2294008 polymorphism (C > T) associated with susceptibility to gastric cancer, bladder cancer, and duodenal ulcers, highlighting its critical role in disease pathogenesis." (PMID 27001215, 2016). "In conclusion, this meta-analysis indicated that the PSCA rs2294008 C>T and rs2976392 G>A polymorphisms might confer increased genetic susceptibility to cancer, especially bladder cancer and gastric cancer." (PMID 26124924, 2015). "When the PSCA rs2294008 CC genotype was used as the reference, the CT genotype and a combination of CT and TT genotypes were associated with an increased stomach cancer risk (adjusted OR = 1.37, 95% CI = 1.07–1.74 for CT, and adjusted OR = 1.30; 95% CI = 1.03–1.63 for CT/TT)." (PMID 25658482, 2015). "The PSCA rs2294008 C>T polymorphism was associated with gastric cancer and bladder cancer, which may be ascribed to cancer specificity." (PMID 26124924, 2015). "SNPs in the Prostate Stem Cell Antigen (PSCA) gene have been found associated with gastric cancer (GC) risk in a genome-wide association study." (PMID 24023815, 2013). "PSCA expression has been found to be downregulated in gastric cancer tissues compared with adjacent normal tissues, suggesting a potential tumor suppressor role in gastric cancer." (PMID 40741413, 2025).